MTOR (mechanistic target of rapamycin kinase)
Diseases named in the same sentence as MTOR in open-access papers (continued):
Sharing a sentence is not in itself a finding about the gene and the disease.
Insulin resistance (continued). "Black women may be predisposed to higher mTOR activation as they have higher prevalence of obesity, insulin resistance, and diabetes compared to White women." (PMID 35608730, 2022). "Indeed, insulin resistance triggered by systemic inflammation has been implicated in the impaired activation of the PI3K/Akt/mTOR signaling pathway." (PMID 34917235, 2021). "mTOR-S6k is one of the most common deregulated pathways in various cancers, and overactivation of the mTOR pathway is closely related to cell growth, metabolism, aging, insulin resistance and obesity, of which are the most common risk factors resulting in MetS." (PMID 33582655, 2021). "Others have suggested that high circulating levels of BCAAs might be one of the causes of insulin resistance through the activation of the mammalian target of rapamycin (mTOR) signaling." (PMID 33805234, 2021). "Increasing evidence has confirmed the efficacy of mTOR inhibitors in treating DN, although they may cause hyperglycemia due to the combination of impaired insulin secretion and insulin resistance." (PMID 32106480, 2020). "Another concept of the etiopathogenesis of schizophrenia is associated with impaired glucose metabolism and insulin resistance with the activation of the mTOR mitochondrial pathway, which may contribute to impaired neuronal development." (PMID 32121669, 2020). "In addition, glucose and leucine increased mTOR/p70S6 kinase phosphorylation and caused insulin resistance, while rapamycin inhibited the changes of phosphorylation and insulin resistance." (PMID 32325903, 2020). "BCAA overload may cause insulin resistance by the activation of mTOR signaling, resulting in persistent IRS-1 phosphorylation by mTORC1 and inhibition of insulin signaling." (PMID 32178221, 2020). "Adipocyte-specific deletion of mTOR also caused insulin resistance and increased hepatic steatosis." (PMID 30318987, 2019). "However, because the roles of mTOR in lipogenesis and insulin signaling are also blocked, common side effects of their use are dyslipidemia and insulin resistance, which are both risk factors for atherosclerosis." (PMID 30609721, 2019). "A hypothesized mechanism of insulin resistance has linked increased BCAA or BCKA levels to the activation of mTOR signaling." (PMID 31277657, 2019). "Lower levels of basal autophagy may impair the ability of neurons and glia to remove aggregated proteins, and so too the activation of mTOR caused by insulin resistance." (PMID 29988365, 2018). "Thus it has been proposed that elevated intake of these amino acids causes insulin resistance through a variety of mechanisms including mTOR activation and generation of short-chain fatty acids." (PMID 25973388, 2015). "MTOR-centric model predicts that this reversible insulin resistance is benevolent and is associated with increased longevity because longevity is promoted not via increased insulin sensitivity, but instead via decreased mTOR pathway signaling." (PMID 25844603, 2015). "These and other studies have suggested that higher tissue and blood concentrations of BCAA may cause or exacerbate insulin resistance in obesity through leucine mediated activation of mTOR." (PMID 25050624, 2014). "Therefore it has been suggested that overnutrition induces insulin resistance, associated with accelerated aging and a shorter lifespan, through the hyper-activation of the mTOR pathway." (PMID 22983440, 2012). "In case B, active mTOR is a cause of insulin resistance and low insulin signaling." (PMID 22683661, 2012). "mTOR has been found to be over-expressed in obesity-linked insulin resistance in mice and to be upregulated by chronic lipid availability in rats, which could be reversed by exercise training leading to AMPK activation." (PMID 21070590, 2011).
Insulin resistance (continued). "Nonetheless, our findings are consistent with the notion that insulin resistance associated alterations in p70S6k regulation may be due, at least in part, to defects in the ability of insulin resistant muscle to activate mTOR following a contractile stimulus." (PMID 20368999, 2009). "In addition, abnormal metabolism of BCAAs is associated with insulin resistance and may contribute to renal fibrosis and inflammatory responses through modulation of the mTOR signaling pathway." (PMID 40647272, 2025). "In addition, BCAAs can continuously activate mTOR signal and damage insulin signal transduction through insulin receptor substrate, and abnormal BCAAs metabolism can cause the accumulation of BCAAs metabolites and eventually lead to insulin resistance." (PMID 36824437, 2023). "The mechanism of BCAA overload causing insulin resistance may be the activation of the protein kinase mTOR (mammalian or mechanistic target of rapamycin), and the increase of acylcarnitine; mTOR is considered to be the main signal of crosstalk between BCAA and insulin." (PMID 36834946, 2023). "Moreover, elevated leucine levels may activate mTOR, causing cardiac insulin resistance and hypertrophy, whereas the inhibition of mTOR results in improved cardiac function in heart failure models." (PMID 35409380, 2022). "Inhibitors of the mammalian target of rapamycin (mTOR), sirolimus, and everolimus, are strongly associated with an alteration in lipid metabolism, due to their mechanism of action; in fact, mTOR complex-1 is involved in lipoprotein synthesis and insulin resistance." (PMID 35887846, 2022). "mTOR may also cause neuronal insulin resistance, glucose deficiency (because insulin and amino acids directly affecting mTOR are the main regulators of ATG), and consequently reduced glucose metabolism, abnormal ATP production, as well as dysfunction and/or death of the cells." (PMID 32121669, 2020). "Consequently, it is hypothesized that the overactivated mTOR increases insulin resistance and the risk of cardiovascular diseases." (PMID 31080547, 2019). "However, the chronic inhibition of mTOR by macrolide rapamycin or other rapalogs has been associated with glucose intolerance and insulin resistance and may even provoke type II diabetes." (PMID 30034573, 2018). "However, recent works sparked questions on whether mTOR activation by physiological changes in the level of BCAAs is sufficient or necessary to cause insulin resistance, and subsequent metabolic disorders." (PMID 27376324, 2016). "Furthermore, activated mTOR/S6K pathway can cause insulin resistance." (PMID 24655348, 2014). "Also, mTOR causes insulin resistance by an additional feedback mechanism." (PMID 22683661, 2012). "Several plant-derived metabolites have been reported to alleviate insulin resistance by modulating the AMPK/mTOR/p70S6K pathways." (PMID 41599356, 2026). "Two other hypothetical mechanisms for these effects include the activation of mTOR and a reduction in insulin resistance." (PMID 41473401, 2026). "The mTOR pathway is one of the branches that has been related to the development of insulin resistance." (PMID 41543803, 2026). "To date, the application of mTOR inhibitors to slow aging is limited by side effects such as insulin resistance and immunosuppression." (PMID 41469379, 2025). "For instance, metabolite formulas like Zexie-Baizhu Decoction and Xiaozhi formula synergistically activate key signaling pathways, including AMPK/SREBP-1c and AMPK/mTOR, effectively reducing hepatic fat accumulation and insulin resistance." (PMID 41383472, 2025). "Activity VitB6 rescues DNA damage treating impaired PI3K, so it can enhance insulin sensitivity and attenuating insulin resistance, and VitB6 has been proved that VitB6 can induced autophagy inhibiting the apoptosis of β‐cells via the mTOR‐dependent pathway." (PMID 40625625, 2025).
Insulin resistance (continued). "The analysis revealed that the genetically elevated mTOR gene level was associated with increased sex hormone-binding globulin (SHBG), a disorder implicated in obesity and insulin resistance." (PMID 40299431, 2025). "Branched-chain amino acids, notably leucine, have been shown to promote mTOR signaling, protein synthesis, and insulin resistance." (PMID 39791169, 2025). "Many papers have investigated the role of Insulin-Like Growth Factor 1 Receptor (IGF-1R) and the mTOR genes in insulin resistance and mTOR pathway in T2DM." (PMID 40533788, 2025). "Metformin, a widely used antidiabetic drug, has shown geroprotective potential by activating AMPK and inhibiting mTOR, thereby improving mitochondrial function and reducing inflammation and insulin resistance—key features of metabolic aging." (PMID 40666427, 2025). "Studies have demonstrated that excessive insulin can induce granulosa cell apoptosis and activate the AKT/mTOR pathway, suggesting a close relationship between the mTOR pathway and insulin resistance in PCOS." (PMID 40937413, 2025). "Previous preclinical studies have already demonstrated that EAAs act through the mTOR-mediated pathway on reducing insulin resistance through insulin-independent intracellular glucose transport." (PMID 40806660, 2025). "The interference of the excessive BCAA in the plasma with the mTOR pathway results in insulin resistance." (PMID 40452790, 2025). "mTOR, a protein kinase that regulates energy balance, cellular growth, and metabolism, has been correlated with a significant improvement in insulin resistance and MASH." (PMID 40643509, 2025). "BCAAs promote adipose tissue activity, NAFLD, and insulin resistance via mTOR-S6K (mammalian target of rapamycin—S6 kinase), and conversely, insulin resistance increases circulating BCAA levels by reduced amino acid metabolization." (PMID 40076626, 2025). "mTOR was found to be linked to isoprenaline-induced cardiac hypertrophy pathogenesis, and several studies defined the hyperactivation of mTOR as a critical mediator of DM pathophysiology by enhancing insulin resistance and inflammation." (PMID 40867548, 2025). "When oxidation is impaired, BCAAs accumulate in the circulation, influencing signaling pathways such as the leucine-mediated activation of mTOR, a key regulator of cell growth, cardiac hypertrophy, and insulin resistance." (PMID 41169508, 2025). "Insulin resistance due to kinase/mTOR inhibitors or corticosteroids needs to be treated with insulin sensitizers, and insulin deficiency due to immunotherapy or post-pancreatitis/pancreatic cancer needs mandatory supplementation of insulin." (PMID 40735043, 2025). "Our findings demonstrated the beneficial effects of VK2 on insulin resistance related skeletal muscle atrophy by promoting protein synthesis via the AKT/mTOR pathway." (PMID 40464168, 2025). "Dysregulation of mTOR signaling results in abnormalities in glucose and lipid metabolism, as well as insulin resistance." (PMID 40881124, 2025). "Sustained mTOR hyperactivation contributes to obesity, insulin resistance, neurodegeneration, and cancer, while AMPK activation counterbalances these effects by restoring cellular energy balance and enhancing metabolic resilience." (PMID 41356921, 2025). "activation of AMPK signaling indirectly increases the expression of GLUT4 to increase glucose uptake and improves IR, and FGF21 inhibits mTOR signaling to ameliorate insulin resistance due to impaired insulin signaling." (PMID 40881124, 2025). "In animal models with insulin resistance, there is increased activation of the mTOR pathway and enhanced IRS-1Ser307/636/639." (PMID 40362446, 2025). "One of the mechanisms through which branched-chain amino acids can promote insulin resistance is the activation of the mammalian target of rapamycin (mTOR) signaling pathway." (PMID 40806262, 2025).
Insulin resistance (continued). "In the context of obesity, the activation of mTOR is often dysregulated, contributing to the accumulation of fat and the development of insulin resistance." (PMID 40218884, 2025). "When the insulin signaling pathway is impaired, FGF21 enhances insulin signaling by activating the AMPK signaling pathway and inhibiting the mTOR signaling pathway to achieve glucose uptake and improve insulin resistance." (PMID 40881124, 2025). "In the genebody region, we also found that pathways related to calcium signaling, insulin resistance, and mTOR signaling were enriched." (PMID 40497962, 2025). "Changes in insulin signaling pathways, such as insulin receptors and substrates, MAPK, JNK, PI3K, AKT, and mTOR, contribute to insulin resistance in GDM." (PMID 40453589, 2025). "Specifically, we will explore how anthocyanins influence key downstream targets of the PI3K/Akt signaling pathway, including FOXO1, GSK3β, GLUT4, and mTOR, as well as their role in reducing oxidative stress, inflammation, and insulin resistance." (PMID 40218884, 2025). "From a molecular perspective, insulin resistance leads to hyperactivation of the PI3K/Akt/mTOR signaling pathway in the liver." (PMID 40430234, 2025). "The precise tuning of mTOR activity across these organs is critical for whole-body metabolic homeostasis, and its dysregulation contributes to the pathogenesis of insulin resistance, obesity, and type 2 diabetes." (PMID 41469379, 2025). "Immunosuppressive agents such as corticosteroids, calcineurin inhibitors, and mTOR inhibitors contribute significantly to these complications, exacerbating metabolic dysfunction, insulin resistance, and lipid abnormalities." (PMID 40142909, 2025). "Elevated mTOR activity contributes to increased fat deposition, insulin resistance, and the development of obesity." (PMID 40076782, 2025). "The results showed that HG inhibits cell proliferation, induces insulin resistance, generates ROS, alters antioxidant enzymes, and promotes oxidative stress, leading to mTOR activation, subsequent autophagy inhibition, and osteocyte apoptosis." (PMID 41300463, 2025). "Another retrospective study found that individuals with hyperlipidemia exhibited elevated mTOR levels, which were positively correlated with insulin resistance, high blood pressure, and BMI." (PMID 40299431, 2025). "GO and KEGG functional enrichment analysis revealed that these genes are primarily associated with insulin resistance, neurotrophin signaling, AMPK, and mTOR signaling pathways." (PMID 40520073, 2025). "The present study implied that EPE diminished visceral obesity and hyperlipidemia and improves insulin resistance by lowering mTOR/S6K1 signaling proteins but elevating insulin sensitivity both in peripheral tissues." (PMID 39329975, 2024). "Since insulin activates the PI3K/Akt/ mTOR pathway analogously to IGF-1, insulin resistance plays an important role in inhibiting the activation of the Akt/ mTOR protein synthesis signaling pathway in muscle atrophy." (PMID 38397848, 2024). "mTOR integrates nutritional and metabolic signals through interactions with the insulin receptor; therefore, excessive mTOR activity can induce insulin resistance." (PMID 39194734, 2024). "Elevated circulating BCAAs can lead to insulin resistance by interfering with lipid oxidation in skeletal muscle and activating the mTOR pathway." (PMID 38348107, 2024). "Overexpression of the mTOR pathway can disrupt cumulus cell interaction, induce insulin resistance, and directly impact follicle growth." (PMID 39464191, 2024). "A study carried out in obese and type 2 diabetic rodents revealed that increased mTOR/p70 S6K signaling contributed to insulin resistance." (PMID 39795155, 2024). "Insulin has been reported to cross the dermal-epidermal junction and affect keratin-forming cells, and the downstream PI3-K/Akt/mTOR signaling cascade is a common and important signaling pathway in obesity, insulin resistance and psoriasis." (PMID 38917217, 2024).
Insulin resistance (continued). "Reduced AMPK activity allows for the activation of mTOR, which, in turn, contributes to insulin resistance." (PMID 39795155, 2024). "More pathways, including insulin resistance and mTOR, were disturbed at 9 W after TAC surgery compared with 3 W after surgery." (PMID 38882003, 2024). "Other signaling pathways, like AMP-activated protein kinase (AMPK), and the mammalian target of rapamycin/p70 ribosomal S6 kinase (mTOR/p70 S6K) signaling pathway was also known to affect insulin resistance." (PMID 39795155, 2024). "Modulation of mTOR pathway was found to participate in the protective role of nanocurcumin in insulin resistance and pancreatic deficits in PCOS rats." (PMID 38302986, 2024). "KEGG analysis revealed pathways such as Fc epsilon RI signaling pathway, sphingolipid signaling pathway, mTOR signaling pathway, asthma, phospholipase D signaling pathway, endometrial cancer, insulin resistance, fatty acid elongation, and autophagy in animals." (PMID 39867577, 2024). "Research has verified that 1,25(OH)2D3 can improve insulin resistance (IR) in trophoblast cells by inhibiting the mTOR signaling pathway, as demonstrated through the establishment of an IR BeWo cell model." (PMID 39749014, 2024). "The dysregulation of the mTOR pathway and the overexpression of Klotho protein contribute to persistent hyperglycemia and insulin resistance." (PMID 39519193, 2024). "On the other hand, unique pathways to which downregulated miRNA gene targets were mapped included insulin resistance, mTOR, and TGF-β signaling." (PMID 39022651, 2024). "The authors suggested an improvement of cell metabolism through reduction of hyperinsulinism, insulin resistance, and potentially inhibition of the mammalian target of rapamycin (mTOR) pathway." (PMID 38281042, 2024). "The role of mTOR/p706SK signaling has been confirmed by many other groups as a critical mechanism involved in the induction of insulin resistance in insulin-sensitive tissues (muscle, fat and liver)." (PMID 36982168, 2023). "The dysregulation of FOXO, MAPK, and MTOR signaling pathways was reported to play important roles in glucose metabolism leading to insulin-resistance-related metabolic disorders found in cancer, but their roles in PPCM and DCM are not well defined." (PMID 37233155, 2023). "The mammalian target of rapamycin (mTOR) is a serine and threonine protein kinase that has an established role in insulin resistance and AMPK directly phosphorylates Raptor, which is a component of mTORC1, to repress mTORC1." (PMID 36677559, 2023). "In this regard, during insulin resistance, the resulting hyperinsulinemia leads to the inhibition of autophagy via the activation of mTOR and the reduction of FOXO1." (PMID 37876013, 2023). "A recent study has reported that miR-155-5p upregulation affects myocardial insulin resistance via mTOR signaling in chronic alcohol-drinking rats." (PMID 36952563, 2023). "Some studies reported that MC stimulates phosphoinositol-3-kinase which phosphorylates Akt and downregulates mTOR to attenuate insulin resistance." (PMID 38096150, 2023). "In skeletal muscle, mTOR over-activation can generate insulin resistance through the degradation of IRS-1 via S6K1, leading to a reduced glucose uptake." (PMID 37298274, 2023). "Palmitate treatment increased the phosphorylation/activation of mTOR and p70S6K, kinases known to be involved in insulin resistance and RA significantly reduced these effects." (PMID 36982168, 2023). "These pathways included the “AGE-RAGE signaling pathway in diabetic complications”, “insulin resistance”, “type II diabetes mellitus”, “adipocytokine signaling”, “longevity regulating pathway”, “mTOR signaling”, and “AMPK signaling”." (PMID 37239845, 2023). "The blockade of central ghrelin receptor can treat NAFLD via the hypothalamic PI3K/Akt/mTOR signaling pathway to improve insulin resistance." (PMID 37760534, 2023).